ERF (ETS2 repressor factor)
Description:
Potent transcriptional repressor that binds to the H1 element of the Ets2 promoter. May regulate other genes involved in cellular proliferation. Required for extraembryonic ectoderm differentiation, ectoplacental cone cavity closure, and chorioallantoic attachment (By similarity). May be important for regulating trophoblast stem cell differentiation (By similarity).
Synonyms: PE-2; PE2; CHYTS; CRS4
Tractability: Antibody: its Gene Ontology location is reachable by antibodies, with high confidence. PROTAC: UniProt records ubiquitination sites on it; ubiquitination databases record sites on it; its protein half-life has been measured.
Gene: Protein-coding gene on chromosome 19 (42,247,569 to 42,255,131, reverse strand). Ensembl gene ENSG00000105722.
Subcellular location: Nucleus
Subcellular location (Human Protein Atlas): Nucleoplasm; Cytosol; Nucleoli; Plasma membrane
Pathways (Reactome):
Cellular responses to stimuli: Oncogene Induced Senescence
Gene Ontology:
Molecular function: DNA-binding transcription repressor activity, RNA polymerase II-specific; protein binding; sequence-specific DNA binding; DNA-binding transcription factor activity, RNA polymerase II-specific; DNA-binding transcription factor activity
Biological process: negative regulation of transcription by RNA polymerase II; cell differentiation; regulation of transcription by RNA polymerase II; regulation of DNA-templated transcription
Cellular component: nucleolus; nucleoplasm; chromatin; cytosol; nucleus
Genetic constraint (gnomAD): Loss-of-function variants: 10 observed, 38.29 expected, observed/expected ratio (o/e) 0.26, 90% interval 0.16 to 0.44. The upper end of that interval is the gene's LOEUF score, 0.44, which puts it in group 1 of 6, group 1 being the genes least tolerant of losing a copy. Missense variants: 621 observed, 744.91 expected, observed/expected ratio (o/e) 0.83, 90% interval 0.78 to 0.89. Synonymous variants: 395 observed, 332.61 expected, observed/expected ratio (o/e) 1.19, 90% interval 1.09 to 1.29.
Gene-disease validity (ClinGen):
ClinGen rates the evidence that ERF causes each of these diseases.
craniosynostosis 4 (autosomal dominant): Definitive. Any craniosynostosis in which the cause of the disease is a mutation in the ERF gene.
Homologues: Orthologues: chimpanzee ERF (99% identical), dog ERF (99% identical), macaque ERF (99% identical), mouse Erf (97% identical), rabbit ERF (97% identical), rat Erf (96% identical), pig ERF (84% identical), tropical clawed frog erf (67% identical), zebrafish erf (66% identical), zebrafish erfl3 (65% identical). Paralogues in human: ETV3 (42% identical), ERFL (30% identical), ETV3L (26% identical), ELK4 (17% identical), ELK3 (16% identical), ELK1 (16% identical), ELF4 (14% identical), ELF2 (14% identical), FLI1 (14% identical), ERG (14% identical), ELF1 (14% identical), ETS1 (13% identical), and 16 more.
Diseases named in the same sentence as ERF in open-access papers:
ERF is named in the same sentence as 61 diseases in open-access papers, as found by Europe PMC text mining. Sharing a sentence is not in itself a finding about the gene and the disease. The quoted sentences say what the papers report.
craniosynostosis (18 papers, 2014 to 2024). Craniosynostosis is defined as the premature fusion of one or more cranial sutures leading to secondary distortion of skull shape resulting in skull deformities with a variable presentation. "The ERF gene variant, linked to craniosynostosis, likely contributes to the observed trigonocephaly." (PMID 38674371, 2024). "For example, there have been at least seven individual cases of associated mutations with CM1 and craniosynostosis in the ETS2 Repressor Factor (ERF) gene." (PMID 39458107, 2024). "Reduced expression of ETS2 repressor factor (ERF) has also been found to cause multi-suture craniosynostosis." (PMID 35451466, 2022). "ERF-related craniosynostosis are a rare, complex, premature trisutural fusion associated with a broad spectrum of clinical features and heterogeneous aetiology." (PMID 32370745, 2020). "Here we describe a boy and his mother with different craniosynostosis patterns, but both with verified intracranial hypertension and heterozygosity for a truncating variant of ERF c.1201_1202delAA (p.Lys401Glufs*10)." (PMID 32370745, 2020). "Crucially, ERF mutation carriers must be followed up regularly in the early years as the associated craniosynostosis is, unusually, indolent and progressive." (PMID 30758909, 2019). "The overall prevalence of ERF mutations in patients with syndromic craniosynostosis is around 2%, and 0.7% in clinically nonsyndromic craniosynostosis." (PMID 30758909, 2019). "In several instances the somatic ERF mutations found in tumor tissue have been identical to the constitutional ERF mutations found in patients with ERF‐related craniosynostosis." (PMID 30758909, 2019). "A recent exome sequencing study of 291 parent‐offspring trios with nonsyndromic midline craniosynostosis reported a novel frameshift ERF mutation in a father and his two offspring each of whom had nonsyndromic metopic synostosis." (PMID 30758909, 2019). "Mutations in ERF have been linked to craniosynostosis, particularly the Muenke syndrome subtype." (PMID 38396475, 2024). "In addition to these genes, recent studies have demonstrated that pathogenic variants in ERF, a molecule that interacts with the RAS/MAPK pathway, can cause craniosynostosis (ERF-related craniosynostosis)." (PMID 37774117, 2024). "Additionally, individual 8 also has a pathogenic heterozygous splicing variant in ERF with similar aberrant splicing effect to a reported ClinVar case with craniosynostosis (accession: VCV001224302.2)." (PMID 38031187, 2023). "ETS2 repressor factor (ERF) insufficiency causes craniosynostosis (CRS4) in humans and mice." (PMID 37175668, 2023). "We speculate that delayed evolution of the craniosynostosis in patients with ERF mutations may result in preservation of a normal head shape because it develops after the period of very rapid skull growth between the third trimester of pregnancy and the end of the first year of life." (PMID 30758909, 2019). "The genetic causes of syndromic craniosynostosis also include alterations in the TWIST1, ERF, and EFNB1 genes, which play a specific role in the development of this condition." (PMID 38396475, 2024). "Pathogenic alterations within the ERF gene have been linked to an infrequent autosomal dominant disorder identified as ERF-related craniosynostosis." (PMID 38674371, 2024). "Syndromic craniosynostosis due to ERF haploinsufficiency presents some unique challenges and opportunities for disease understanding and management." (PMID 37175668, 2023). "Custom genes panel allowed us to detect novel pathogenic variants–p.Arg132* in the ERF gene (P129), and p.Ser391* in the ZIC1 gene (P131), resulting in Craniosynostosis 4 and Craniosynostosis 6, respectively." (PMID 35591945, 2022). "Pharmacological factors that augment ERF suppressor activity were tested in the mouse model to assess their ability to ameliorate the ERF-related craniosynostosis (to be published elsewhere)." (PMID 34564098, 2021).
craniosynostosis (continued). "This is clearly shown by the variants of NSD1 in cases 1 and 2, who were later assigned as affected by Sotos syndrome, and the variants identified in ERF, FGFR1, and FGFR3, all genes associated with craniosynostosis and, rather frequently, Chiari malformation." (PMID 33337535, 2021). "Recent data indicate that ERF haploinsufficiency leads to craniosynostosis (CRS-4) in both humans and mice." (PMID 34564098, 2021). "Augmentation of pERK1/2 signaling either through overactivation of FGFRs, downregulation of its inhibitors, or downregulation of ERF that regulates the export of pERK from the nucleus, all result in craniosynostosis." (PMID 32662771, 2020). "Our work provides supplementary evidence in support of previous phenotypic descriptions of ERF-related craniosynostosis, particularly late presentation, an evolving synostotic pattern and variable expressivity even among affected family members." (PMID 32370745, 2020). "All patients with Chitayat syndrome reported to date have had a specific heterozygous ERF p.Tyr89Cys missense substitution in the ETS domain, very close to mutations reported in ERF‐related craniosynostosis." (PMID 30758909, 2019). "A reduced dosage of ERF protein leading to craniosynostosis may suggest an interaction between the RAS and the FGFR signaling pathways as multiple independent authors have shown." (PMID 37774117, 2024). "However, the role of ERF activation for the development of craniosynostosis is still not well understood and more studies are needed to elucidate these mechanisms." (PMID 37774117, 2024). "Identification or development of more specific activators of the residual ERF suppressor function could be a potent approach not only in ERF-related craniosynostosis but likely in other FGF/MAPK-related craniosynostosis disorders." (PMID 37175668, 2023). "As our cohort demonstrates, the absence of a clearly abnormal skull shape in patients with ERF mutations does not exclude the possibility of craniosynostosis." (PMID 30758909, 2019). "ERF‐related craniosynostosis was first described in 2013 in 12 unrelated families accounting for 7.1% of a cohort of 127 patients with undiagnosed clinically syndromic craniosynostosis, and 2.9% of a total cohort of 412 undiagnosed patients with syndromic or nonsyndromic craniosynostosis." (PMID 30758909, 2019). "However, also in this case interesting examples of co-occurrences may be found, often involving genes known to be associated with Psoriasis, such as QTRT1, as well as genes related to other diseases, e.g. ERF, implied in complex craniosynostosis, and ISOC2, biomarker of Osteoarthrosis Deformans." (PMID 37021928, 2023). "Our data suggest that the ERF level is an important regulator of cranial bone development and that pharmacological modulation of its activity may represent a valid intervention approach both in CRS4 and in other syndromic forms of craniosynostosis mediated by the FGFR-RAS-ERK-ERF pathway." (PMID 37175668, 2023).
prostate carcinoma (5 papers, 2019 to 2024). A carcinoma that arises from epithelial cells of the prostate gland. "Capicua (CIC) and ETS2 repressor factor (ERF) are co-deleted in aggressive prostate cancer (PCa) and associate with worse clinical outcomes." (PMID 36383412, 2022). "In the association study of Finnish prostate cancer cases and controls the ERF variant was observed in three cases and three controls (OR = 0.68, 94% CI 0.14, 3.39, p = 0.641)." (PMID 34063511, 2021). "A genomic analysis of localized prostate cancers on a group of 102 AAM cases led to the identification of recurrent loss-of-function mutations of ERF, an ETS transcriptional repressor, in 5% of cases." (PMID 31366128, 2019). "Notably, CIC and ERF have been shown to co-regulate the expression of ETV1 in prostate cancer, where their combined loss and the subsequent increase in ETV1 expression contribute to disease progression." (PMID 37345142, 2023). "Targeting ETV1 in CIC and ERF-deficient prostate cancer limits tumor growth." (PMID 36383412, 2022). "A rare, shared variant in ERF was also found to show significant association with bladder cancer risk in an independent population, was present in other prostate cancer-affected members in the pedigree, and showed evidence for altering the function of the associated protein." (PMID 34063511, 2021). "Interestingly, 2–4% of prostate cancers display mutational alteration of the ERF gene and ETS transcriptional repressor." (PMID 31366128, 2019). "Interaction between AR and any one of these factors has not been previously reported in the context of breast cancer, but JUNB and ERF have been identified as AR interacting proteins in two LNCaP-derived cell line models of prostate cancer." (PMID 38317241, 2024). "Capicua (CIC) and ETS2 repressor factor (ERF) mutually suppress malignant phenotypes in human prostate cancer (PCa)." (PMID 36383412, 2022). "In existing prostate cancer cohorts ERF deletions were seen in 3% of primary prostate cancers and deletions of ERF were seen in 3–5% of lethal castration-resistant prostate cancers." (PMID 34063511, 2021). "ERF has been identified as a prostate cancer tumor-suppressor gene in a study of localized primary prostate tumors from 102 African-Americans in which recurrent loss-of-function somatic mutations in ERF were observed in 5% of cases." (PMID 34063511, 2021). "This evidence supports ERF (ETS2 Repressor Factor) as a bladder and prostate cancer predisposition gene." (PMID 34063511, 2021). "In combination with previous work suggesting ERF as a prostate cancer gene, these observations additionally confirm the role of this rare ERF variant in familial prostate cancer." (PMID 34063511, 2021). "ERF has been reported to be downregulated in prostate cancer." (PMID 34063511, 2021). "ERF mutations cause decreased protein stability and occur in prostate cancers without ERG upregulation." (PMID 31366128, 2019). "Hence, androgen-induced interactions between AR and JUNB or ERF may confer growth inhibitory actions that are conserved across breast and prostate cancer contexts, but this requires future investigation." (PMID 38317241, 2024). "One variant in ERF (ETS Repressing Factor) was significantly associated with bladder cancer risk in an independent population, was observed to segregate with bladder and prostate cancer in relatives, and showed evidence for altering the function of the associated protein." (PMID 34063511, 2021). "Thus, loss of ERF activity by rare genomic loss-of-function mutations or by competition with the TMPRSS2-ERG oncogenic product leads to activation of the androgen receptor pathway and prostate cancer." (PMID 31366128, 2019). "ERF and CIC were also recently shown to coordinate to regulate ETV1 expression in prostate cancer cells, further supporting the notion that the two proteins function similarly and, at least in one context, cooperatively." (PMID 37345142, 2023).
fungal infection (4 papers, 2023 to 2025). "Furthermore, distinct TFs specifically regulate host gene expression under various biotic stressors, with MYB/NAC proteins mainly for bacterial infections and GATA and ERF factors for virus/virus and fungal infections, respectively." (PMID 39524930, 2024). "Recent studies have emphasized the significance of ERF and MYB families in regulating responses to biotic stress with particular referment to B. cinerea and fungal infection, including the regulation of defense genes via JA/ET pathways." (PMID 39997418, 2025).
prostate tumors (4 papers, 2017 to 2022). "Leveraging mutational profiling data from multiple PCa cohorts, we previously observed concurrent loss of the ETS2 repressor factor (ERF) in CIC-deficient prostate tumors." (PMID 36383412, 2022). "Based on these results, we hypothesized that a decrease in ERF expression in prostate tumor samples can cause activation of the ETS transcriptional program similar to ERG activation." (PMID 28750683, 2017). "Here, we show that two neighboring transcription factors, Capicua (CIC) and ETS2 repressor factor (ERF), which are co-deleted in human prostate tumors can drive prostate oncogenesis." (PMID 36383412, 2022). "Very recently, a study of the exomes of African-American PCa patients suggested the role of ERF as a prostate tumor suppressor gene." (PMID 28750683, 2017). "We report known prostate tumor regulatory drivers and nominate novel transcription factors (ERF, CREB3L1, and POU2F2), which are supported by functional validation." (PMID 28750683, 2017). "Inactivating point mutations and deletions of the ETS factor ERF were recently identified in about 4% of prostate tumors, and these mutations are able to recapitulate phenotypes of ERG overexpression; furthermore, ChIP-seq analyses indicate that ERF and ERG compete for binding throughout the genome." (PMID 30603056, 2018). "The significant enrichment of the ERF gene expression signature in ERF and ERG binding targets validates our network predictions and supports our hypothesis that differential expression of ERF due to SVs can activate the ETS transcriptional program in prostate tumor samples." (PMID 28750683, 2017).
viral infection (4 papers, 2016 to 2025). "It is hypothesized that AP2/ERF-ERF may be involved in the regulation of key metabolic pathways in plants after PVY infection to resist virus infection." (PMID 38511006, 2024). "Notably, eight ERF genes in our data were strongly affected by viral infection and the resulting expression levels in the CGMMV-inoculated flesh were more than two fold those of the control." (PMID 29196660, 2017). "This aligns with the previous findings demonstrating that the ERF, NAC, WRKY, and MYB transcription factors play key regulatory roles in viral infection." (PMID 41157706, 2025). "In addition to the ERF genes and ORA47, the WRKY genes, a type of genes that are induced after virus infection, displayed a different expression pattern after TCV infection." (PMID 27782158, 2016).
breast carcinoma (3 papers, 2024 to 2025). "Of particular interest were three DNA-binding factors associated with AR on chromatin in all breast cancer contexts: GATA3, JUNB, and ERF." (PMID 38317241, 2024). "Furthermore, in vitro evidence implicates ERF in transcriptional repression of the c-Myc oncogene in ER+ breast cancer cells." (PMID 38317241, 2024). "In addition to GATA3, two other DNA binding transcription factors, JUNB and ERF, were identified as AR interacting proteins in all breast cancer cell line models." (PMID 38317241, 2024). "In breast cancer, JUNB and ERF are transcriptional repressors downregulated by ER signaling, a feature that facilitates ER-induced transcription of proliferation genes." (PMID 38317241, 2024).
Ewing sarcoma (3 papers, 2019 to 2024). A small round cell tumor that lacks morphologic, immunohistochemical, and electron microscopic evidence of neuroectodermal differentiation. "Paired tumor/normal exome sequencing also identified the presence of an ERF p.Met76IlefsTer5 somatic variant and multiple copy number alterations, consistent with a diagnosis of Ewing sarcoma." (PMID 36980535, 2023). "Somatic loss‐of‐function mutations in ERF have been reported in tumors including prostate, stomach and colorectal adenocarcinomas and Ewing's sarcoma at frequencies of 3–5%." (PMID 30758909, 2019).
iron deficiency (3 papers, 2017 to 2025). "Several transcription factors, especially from the NAC, AP2/ERF, and bHLH families, actively reacted to drought and iron deficiency and might play a crucial role in linking hormone signaling and Fe transport under drought stress." (PMID 41303435, 2025). "Consistent with our results, several ERF genes are also activated in response to early iron deficiency in iron deficiency-tolerant Malus xiaojinensis, suggesting that the ethylene signal pathway plays an important role in iron-tolerant species under iron deficiency conditions." (PMID 28694816, 2017). "Sixty-seven gene families were discovered to be involved in the control of iron deficiency stress by examining differentially expressed transcription factors, including the WRKY, MYB, AP2/ERF-ERF, bHLH, NAC, C2H2, bZIP, HB-HD-ZIP, and GARP-G2-like families." (PMID 35371147, 2022).
Bladder Cancers (2 papers, 2021 to 2023). "Analysis of available data from an independent population for the resulting set of candidate variants identified a variant in ERF (rs144812092) that was significantly associated with bladder cancer risk." (PMID 34063511, 2021). "The ERF variant rs144812092 was originally observed in a pair of bladder-cancer-affected first cousins." (PMID 34063511, 2021). "Only 2 of the variants independently showed significant association with bladder cancer: c19orf40 (rs36017455, OR = 2.33, p = 0.009) and ERF (rs144812092, OR = 3.64, p = 0.04)." (PMID 34063511, 2021).